CRP (C-reactive protein)
Diseases named in the same sentence as CRP in open-access papers (continued):
Sharing a sentence is not in itself a finding about the gene and the disease.
infection (continued). "CRP is synthesized by the hepatocytes in a response to the infection, as a part of the innate immunity." (PMID 33521320, 2021). "Laboratory indicators, such as erythrocyte sedimentation rate (ESR), C-reactive protein (CRP), and blood cell count, were tested at appropriate time points to ensure eradication of the infection." (PMID 34863237, 2021). "Different triggers, such as infection, inflammation pathways, and autoimmune responses, can induce elevated levels of CRP and ESR." (PMID 34679434, 2021). "First, CRP starts to rise after 12–24 h and peaks at 48–72 h after the onset of infection, while PCT increases within 2–6 h and peaks within 6–24 h after the onset of infection." (PMID 34066811, 2021). "Particular attention should be paid to the determination of the infection parameters such as leukocyte count, C-reactive protein (CRP), and the procalcitonin (PCT)." (PMID 33755737, 2021). "On admission, the median of the infection parameters C‐reactive protein (CRP), interleukin (IL)-6, brain-type natriuretic peptide (BNP) and procalcitonin were above the normal range in the peripheral blood." (PMID 33666682, 2021). "NS is generally diagnosed according to the combination of clinical presentation and laboratory diagnosis, including cultures and infection markers, such as CRP, PCT, WBC, and so on." (PMID 33485295, 2021). "The presence of infection was associated with increased WBC (p = 0.001; DOR = 3.2 [1.6–6.5]), but elevated CRP concentrations were more useful (p < 0.0001; DOR = 4.0 [2.3–7.7])." (PMID 33947369, 2021). "Since its first description as a potential infection biomarker in patients after trauma, pancreatic stone protein has repeatedly been shown to perform better than CRP and at least as well as PCT in identifying patients with infection." (PMID 34049579, 2021). "Serum CRP is a systemic inflammatory response protein, which can reflect the infection status of neonates." (PMID 34745505, 2021). "Hepatocytes produce CRP in response to leukocyte-derived cytokines induced by infection, inflammation, or tissue damage –." (PMID 34786318, 2021). "Lower magnitude CRP elevations have been associated with increased risk of infection, suggesting that greater HRV decreases and CRP increases would equate to a protective inflammatory or immunologic response." (PMID 34236995, 2021). "The range of CRP levels at enrollment was wide, and it was unable to adjust for confounding factors such as subclinical infection." (PMID 33670636, 2021). "CRP is an exquisitely sensitive systemic marker of acute-phase response in inflammation, infection, and tissue damage." (PMID 34940584, 2021). "After acute stroke, CRP level is elevated due to tissue injury and infection, proportional to the severity of acute events." (PMID 33967939, 2021). "As many as 23 of 25 patients with postop infection had a CRP/alb ratio that exceeded the median of our data." (PMID 33740951, 2021). "Infections during pregnancies are common and CRP is frequently measured as a surrogate marker of infection." (PMID 34408755, 2021). "The maximal postoperatively measured CRP was higher in the infection group (Mann–Whitney, p = 0.046), while the mean postoperative CRP did not yield differences." (PMID 34768504, 2021). "Laboratory parameters of infection were measured during the cement spacer retention period: C-reactive protein (CRP), sedimentation rate (SEDIM), and white blood cell (WBC) count." (PMID 33859919, 2021). "The blood concentration of procalcitonin rises about 2–3 h after the onset of infection and the half-life of procalcitonin is approximately 20–24 h, making it easier to maintain high concentrations in comparison with CRP which has a half-life of 4–6 h." (PMID 33566306, 2021). "Compared with widely used infection biomarkers, CRP had a lower sensitivity, specificity, and LR+ than PCT." (PMID 34066811, 2021).
infection (continued). "As a sensitive indicator of inflammation, CPR detection is quick and convenient, and CRP increase is positively correlated with the severity of infection or inflammation." (PMID 34233608, 2021). "For CRP, cut-offs of 41.5 mg/L and 21.8 mg/L were found to diagnose a confirmed infection with 80 and 90% sensitivity, which were accompanied by specificities of 53 and 32%." (PMID 35155322, 2021). "C-reactive protein is a marker for infection, increases in response to systemic inflammation and is mainly synthesized by hepatocytes in response to proinflammatory cytokines (IL-1, IL-6, and TNF-α)." (PMID 33937367, 2021). "For this purpose, we assessed the diagnostic accuracy of daily measured PCT, CRP, and WCC to diagnose infection in 65 consecutive ECMO runs at our center." (PMID 35155322, 2021). "C-reactive protein (CRP) is a highly sensitive marker of systemic inflammation that is mainly released by hepatocytes in response to tissue injury, infection or inflammation." (PMID 35070979, 2021). "CRP is a common biomarker of inflammation and infection for heart diseases, and serum CRP level is used to determine disease progression or treatment effectiveness." (PMID 35054241, 2021). "CRP level in patients with post-traumatic infection supports the positive microbial findings in this cohort and was significantly higher (day 3: inf+PT 15.3 mg/dL > inf-PT 6.7 mg/dL, p = 0.001) comparing trauma patients without infection." (PMID 34568354, 2021). "CRP is a well-known and widely used marker for infection, despite its recognized drawbacks for specificity and sensitivity." (PMID 34830673, 2021). "CRP is predominantly produced by the liver in response to IL-6, following injury, infection or trauma." (PMID 34769069, 2021). "CRP is produced mainly by hepatocytes but also by cardiovascular tissues upon infection or tissue injury." (PMID 34046195, 2021). "And it brings new knowledge to the fact that pregnant women can remain asymptomatic or when they have symptoms, fever is their main one, accompanied by the elevated serum CRP and that cesarean delivery is a recurrent outcome in this type of infection." (PMID 34933389, 2021). "The median concentration of CRP in the synovial fluid for the infection group was 9.93 mg/l and was significantly higher (p < 0.001) than the aseptic group with a median concentration of 3.58 mg/l." (PMID 34372816, 2021). "The level of CRP in the blood is proportional to the degree of synthesis in the liver; thus, the blood level of CRP has been used for the diagnosis and treatment monitoring of infection or inflammatory disease." (PMID 34362075, 2021). "PCT and CRP have a good correlation with disease activity, and can be a good indication of the type of infection." (PMID 34836530, 2021). "CRP is an acute-phase protein synthesised in response to pro-inflammatory cytokines during infection and injury." (PMID 34739504, 2021). "The level of CRP mostly depends on the amount of tissue damage currently occurring, and it can rise 1000-fold after infection or tissue damage within 24 to 48 h." (PMID 34281552, 2021). "Trainees more often mentioned how CRP results can appear normal for a child at the beginning of a serious infection, while consultants seemed more concerned with the difficulty of interpreting intermediate CRP results." (PMID 33972339, 2021). "The maximum CRP predicted an infection with a sensitivity and specificity of 75% and 56.9%, respectively, while a binary logistic regression reached values of 75% and 80%." (PMID 34768504, 2021). "Potential impact of inflammation on the HC microbiome was minimized by excluding HCs with infection or elevated inflammatory markers (CRP, white cell count, body temperature)." (PMID 33868230, 2021). "Patients with higher CRP/alb ratio were significantly more likely to have postoperative infections than patients with lower CRP/alb ratio (p = 0.026)." (PMID 33740951, 2021).
infection (continued). "As an acute phase protein that increases during the inflammatory process, serum CRP concentrations are commonly used as a surrogate marker for infection." (PMID 34930183, 2021). "Higher CRP levels represent severe inflammation and infection, leading to a higher in-hospital mortality rate." (PMID 34407879, 2021). "All septic patients received empirical antibiotic treatments at ICU admission mainly based on signs of infection in routine blood tests, including elevated counts in white blood cells and neutrophils, and increased levels of blood CRP and PCT." (PMID 34915851, 2021). "As an acute-phase protein, CRP is a rapidly elevated protein in the presence of infection, inflammation, and trauma." (PMID 33575324, 2021). "A multivariance analysis confirmed that TSH level was not significantly influenced by any of the parameters in question (type of infection, fever, elevated value of CRP, WBC, elevated count of lymphocytes or neutrophils)." (PMID 33924694, 2021). "Several conditions that increase CRP have been observed including inflammatory processes, cancer, pregnancy and infection." (PMID 33794783, 2021). "The aim of this study was to retrospectively study the reliability of PCT and CRP in cancer patients admitted for fever and to identify the appropriate cut-off values for ruling out infection." (PMID 33777975, 2021). "CRP mediated 25% of the association of CAD+AMI+ with all-cause mortality (P = 0.033) and 36% of the association with infection-related mortality (P = 0.042)." (PMID 34315941, 2021). "The level of albumin was negatively correlated with infection prognosis in all patients (P = 0.03), and negatively correlated with neutrophil count and CRP (P = 0.008, P < 0.001)." (PMID 34712677, 2021). "A CRP of ≥25.5 mg/L diagnosed proven or suspected infection with a sensitivity of 80%, with a specificity of 37%." (PMID 35155322, 2021). "The high-level and the low-level group differed significantly in infection laboratory parameters (CRP (mg/dL) 20.18 ± 11.71 vs. 5.75 ± 5.33) and renal function [glomerular filtration rate (mL/min/1.75 m2) 40.85 ± 26.74 vs. 120.50 ± 70.48]." (PMID 34943664, 2021). "Earlier studies found that patients with preoperative infection had higher rates of postoperative infection, and patients with preoperative bacterial infection often had higher baseline CRP levels, which is in agreement with our findings." (PMID 34439862, 2021). "CRP levels are known to increase significantly during acute inflammatory processes and host responses to infection." (PMID 34840450, 2021). "We obtained unpublished results, including adjustment for age, sex, body mass index, smoking, alcohol use, and socioeconomic status and suspected infection (CRP > 10 mg/L)." (PMID 34050185, 2021). "In this study, the average CRP concentrations in dogs with E. canis, B. canis, and H. canis single infections were higher than the reference range (>30 mg/L)." (PMID 34566333, 2021). "A simple three-gene PCR signature was derived, which has superior ability to differentiate viral from other infection presentations compared with existing biomarkers, such as C-reactive protein and leukocyte count." (PMID 34423323, 2021). "Previous studies on FDG-PET/CT in non-ICU patients found a statistically significant relation between inflammatory parameters such as CRP and leukocyte count and detecting an infection focus on FDG-PET/CT." (PMID 33827655, 2021). "Although CRP is widely used as a surrogate marker of infection and inflammation in healthcare, specific reference intervals for pregnancies have not been established." (PMID 34408755, 2021). "Data were available for 13 further individuals with infections whose initial and follow-up CRP levels were both > 100 mg/L (means, SD, 199.2 ± 59.0 and 159.4 ± 40.7 mg/L respectively, (p = 0.055)." (PMID 34446820, 2021).
infection (continued). "Conversely, patients who died from COVID‐19 in our registry showed significantly higher levels of preinfection neutrophils and CRP than those who survived the infection." (PMID 34121360, 2021). "CRP level was found to be more pronounced in the HIV–MTb co-infection group compared to MTb infection alone." (PMID 34295314, 2021). "CRP levels were significantly higher in the infection group [18.3 (8.9–32.2) mg/dL] than in the non-infection group [5.7 (3.7–10.8) mg/dL)] (P = 0.001)." (PMID 33676477, 2021). "There is accumulating evidence that CRP, beyond its role as a marker for infection, can be actively involved in the propagation of inflammation, particularly when bound to extracellular vesicles released from activated platelets." (PMID 33790693, 2021). "The normalisation of CRP after a replacement surgery is of paramount importance for the operating surgeon as it is the rising trend of CRP after touching the normal baseline values that help alert the surgeon for the possibility of delayed infection." (PMID 34429835, 2021). "Based on the results of this study, the PCT and PSPN were superior to CRP which used in the clinical practice to diagnose infection." (PMID 34324506, 2021). "To date, few studies focused on the prediction of the severe and extremely severe infections based on CRP, IL-6, or NRL." (PMID 33575324, 2021). "Infection parameters, measured by C reactive protein (CRP; standard values < 0.5 mg/dl) levels at the time of admission, were elevated in most of the patients (70%), showing mean CRP levels of 1.6 (SD 1.6)." (PMID 33037537, 2021). "Complete healing was defined as normalization of the infection parameters (normalization of leukocyte count and significant fall of C-reactive protein) was achieved in 211 (89%) of cases." (PMID 34439638, 2021). "Thirteen additional participants with infections had a CRP > 100 mg/L that persisted at review (199.2 ± 59.0 and 159.4 ± 40.7 mg/L, p = 0.055)." (PMID 34446820, 2021). "In terms of infection-related parameters, 85.5% of patients had increased CRP (higher in the ICU group), and 80.1% of cases had increased erythrocyte sedimentation rate (ESR)." (PMID 34024768, 2021). "We supposed that the negative correlation between ApoA and the acute inflammatory protein CRP was related to the anti-infection activity of ApoA-I." (PMID 34277446, 2021). "CRP is a widely used and important acute-phase serum protein for monitoring infection in the clinic." (PMID 34992504, 2021). "CRP was identified in the 1930s and is synthesized in the liver and released in response to infection, trauma and immune disorders." (PMID 34675320, 2021). "It induces the hepatic acute-phase response and mediates the production of C-reactive protein (CRP) during infection." (PMID 33804790, 2021). "CRP is an acute-phase proinflammatory cytokine and a sensitive biomarker of infection and tissue damage." (PMID 33557785, 2021). "Given the spatial and temporal proximity of both antibodies and CRP during infection and inflammation, this provides more evidence for the notion that CRP not only initiates complement, but acts as an amplifier after localised activation at sites of acidosis." (PMID 34975846, 2021). "Different blood biomarkers such as procalcitonin (PCT), C-reactive protein (CRP), or white blood cells (WBC) have been suggested as possible candidates to help in predicting/identifying patients at risk for poststroke infections." (PMID 34200779, 2021). "Clinically, CRP has good value in screening critically ill patients, diagnosing infections, and evaluating patient response to antibiotic treatment." (PMID 34233608, 2021). "With regard to laboratory testing related to SSI, ESR and CRP, as inflammatory markers, are two commonly used indicators to indicate improvement or progression of infection, especially CRP with more sensitivity." (PMID 34243798, 2021). "Hs-CRP level is elevated in the circulation in response to tissue damage, acute inflammation, and infection." (PMID 34711013, 2021).
infection (continued). "Looking back on our study, we noted a statistically significant change in CRP, as well as in the number of neutrophils and lymphocytes during hospitalization, which implied the effect of infection control through medical treatment." (PMID 34069451, 2021). "CRP is a positive reactant synthesized by the liver during the acute phase and increases in level in response to inflammation and infection." (PMID 34726101, 2021). "In multivariable analysis of the infection group, higher CRP per mg/L increase at time of TLE (HR 1.01; 95% CI 1.00–1.01; P <.001) predicted mortality." (PMID 33984526, 2021). "In this cohort, non-severe and severe groups showed significant differences in white blood cells, neutrophils, lymphocytes, basophils and platelets counts, as well as in infection related parameters such as CRP and serum cytokine IL-6." (PMID 33504359, 2021). "IL-6 stimulates the expression of C-reactive protein (CRP), which is an acute phase protein used as a serum biomarker for severe infection of this type of coronavirus." (PMID 33919780, 2021). "The International Consensus on Orthopedic Infections and numerous studies have described CRP trend as a critical parameter for assessing PJI treatment response after the first-stage resection in a two-stage exchange arthroplasty." (PMID 34856956, 2021). "The CRP levels showed the lowest AUC of all the parameters for predicting infection (p-values are <.05)." (PMID 34727802, 2021). "In this study, wereport a convenient analytical method for a full-rangequantification of the C-reactive protein (CRP), a blood biomarkerof infection and cardiovascular events." (PMID 34056444, 2021). "The synovial CRP levels were significantly higher in the infection group than in the aseptic group (median: 9.93 mg/l vs 3.58 mg/l; p < .001)." (PMID 34372816, 2021). "Combining PSP with CRP increased the accuracy of detecting infection from an AUC 0.81 to 0.90, a value that is usually considered as very good and among the highest AUCs reported for this setting." (PMID 34049579, 2021). "This suggests that the circulatory system CRP is detected by spreading to the synovial fluid through increased vascular and synovial permeability due to infection." (PMID 34372816, 2021). "Of these, 14 (26.92%) showed evidence of low-grade inflammation (CRP > 3 mg/L but ≤ 10 mg/L), and 17 (32.69%) had evidence of suspected infection (CRP > 10 mg/L)." (PMID 32950620, 2021). "The intra-articular drain can give information about the joint fluid (clear or cloudy) and the infection blood parameters should drop after surgery (CRP, leucocytes, PCT) during antibiotic administration." (PMID 33755737, 2021). "In this study, elevated CRP which is induced by IL-6, was present after infection with all three strains of B. pseudomallei." (PMID 33571211, 2021). "PCT values increase earlier than CRP values in severe infections and also fall quicker after appropriate antibiotic treatment." (PMID 34830040, 2021). "First, CRP has been established as a general biomarker of inflammation and infection in clinical practice." (PMID 33679775, 2021). "One of the main SIRS markers, CRP, was dramatically elevated to 64.9 (39.7;80.1) and 71.4 (36.1;109.5) in patients with moderate and severe infection, respectively." (PMID 34696395, 2021). "Application of antibiotic therapy for more than six weeks and normalized CRP showed a correlation with favorable outcomes, whereas concomitant infections showed a correlation with unfavorable outcomes." (PMID 34439638, 2021). "Two subjects from YAC group and one from CON group had concentrations of CRP above 10 mg/L, suggesting the presence of acute inflammation or infection at baseline." (PMID 34033301, 2021). "Although there was a significantly lower chance of having a PJI with an implant age of > 5 years combined with a CRP < 5 mg/L, an infection was still present in 3 out of 39 cases (8%)." (PMID 33559723, 2021).